SOX9 (SRY-box transcription factor 9)
Diseases named in the same sentence as SOX9 in open-access papers (continued):
Sharing a sentence is not in itself a finding about the gene and the disease.
cancer (476 papers, 2006 to 2026). A tumor composed of atypical neoplastic, often pleomorphic cells that invade other tissues. "SOX9 expression is closely associated with the expression of immune checkpoints across various cancer types." (PMID 41293317, 2025). "Among these potential interactors, SOX9, a well-known transcription factor associated with cancer stem cells, has emerged as a key candidate." (PMID 40374599, 2025). "Literature indicates that OSCC cells interact with cancer-associated fibroblasts (CAFs) through the TGF-β/SOX9 axis during cancer progression." (PMID 41235252, 2025). "For example, SOX9 was found highly expressed in various cancer types and thus associated with unfavorable clinical outcome." (PMID 35779228, 2023). "Another important gene associated with EMT and cancer metastasis is SOX9, which specifically activates the HIPPO-YaP pathway." (PMID 36980876, 2023). "Many of the pathways enriched in the C2/C5 clusters were also implicated in other cancers previously associated with SOX9 expression." (PMID 37488435, 2023). "SOX9 has strong oncogenic properties associated with the growth and metastasis of several types of cancer." (PMID 36139487, 2022). "We found the expression of SOX9 correlates with cancer-associated fibroblast immune infiltration in immune cells by Timer2.0." (PMID 36003340, 2022). "Here, we aimed to explore the role and underlying mechanism of a SOX9 in the regulation of cancer cell death using in vitro and in vivo approaches." (PMID 35159173, 2022). "The expression of SOX9 correlates with cancer-associated fibroblast immune infiltration in immune cells." (PMID 36003340, 2022). "Genomic analyses of human CRC from The Cancer Genome Atlas and Cancer Cell Line Encyclopedia indicated that the majority of SOX9 mutations are heterozygous, preserving a WT copy of the gene." (PMID 37621863, 2022). "The expression of SOX9 correlates with cancer-associated fibroblast (CAF) immune infiltration in immune cells." (PMID 36003340, 2022). "Increased SOX9 expression has been associated with clinical stage and poor prognosis in these cancers." (PMID 35884771, 2022). "Combinatory treatment with Sorafenib, mostly resulted with downregulation of hub proteins JUN, INSIG1, MDM2 and SOX9 associated with cancer cells." (PMID 35331184, 2022). "Overexpression of SOX9 in cancers is associated with the regulation of cell proliferation and metastasis." (PMID 35201494, 2021). "3-Methylcholanthrene (MCA)-induced cSCC in Flii overexpressing mice showed increased markers of cancer metastasis including talin and keratin-14 and a significant increase in SOX9 alongside a reduction in Flii associated protein (Flap-1)." (PMID 34948000, 2021). "The developmental regulator SOX9 is widely linked to cancer cell proliferation, progression, survival and evasion of senescence in different cancers." (PMID 34163029, 2021). "The developmental regulator SOX9 is linked to cancer progression mainly as a result of its role in the regulation of cancer stem cells (CSCs)." (PMID 31941916, 2020). "We also used the IPA Regulator Effects module to predict cancer-specific networks encoded by our 350 gene set and we selected the networks in which both p62 and SOX9 were target molecules." (PMID 31959131, 2020). "The loss of FBW7 function increases SOX9 protein levels, increasing the malignancy of cancer and resistance to cisplatin." (PMID 32333246, 2020). "Overall, these results suggest a pathogenic role for SOX9 in promoting tumorigenesis downstream of cancer‐specific KEAP1 mutations." (PMID 33173725, 2020). "In this context of cancer development, SOX9 expression is also known to be directly linked to Wnt/β-catenin signaling in GC17." (PMID 32277152, 2020). "Given that the Kelch domain deletion showed the strongest effect on SOX9 binding, we examined three cancer‐associated KEAP1 mutations within this domain for their effects on SOX9 stability." (PMID 33173725, 2020).
cancer (continued). "A significant portion of cancer‐associated mutations in KEAP1 inhibits its ubiquitin ligase activity toward SOX9 and these mutations promote cancer cell growth and tumorigenesis through the stabilization of SOX9." (PMID 33173725, 2020). "Another important regulator of SOX9 is the glycosyltransferase ST6Gal-I which adds α2-6-linked sialic acids to substrate glycoproteins and it is known that its upregulation in cancer cells confers stemness characteristics." (PMID 31057614, 2019). "In previous studies using biopsies of BC, 75% positive immunostaining of SOX9 was observed in the nucleus of cancer cells and the expression was significantly associated with the advanced pathological grade and clinical stage." (PMID 31057614, 2019). "Previous studies using biopsies of BC have shown that 75% positive immunostaining of SOX9 is observed in the nucleus of cancer cells and this expression is significantly associated with the advanced pathological grade and clinical stage." (PMID 31057614, 2019). "COSMIC analysis showed that, from a total of 46,601 unique cancer samples, 572 samples have mutations in SOX9 and the most frequent mutation type is missense substitution (38.81%) of which 113 (33.63%) are C>T transitions." (PMID 31057614, 2019). "SOX9 has been implicated in cancer in many tissues and its role has been shown to be varied and context dependent." (PMID 29484136, 2018). "High expression of SOX9 in the nuclei of iCCA cancer cells was significantly associated with shorter survival time (P = 0.0039)." (PMID 30420613, 2018). "SOX9 has been implicated as a cancer stem cell marker with the ability to drive cancer growth and promote cancers metastatic ability." (PMID 29121666, 2017). "Dysregulation of SOX9 has been further implicated in cancer progression as an oncogene, which promotes cell proliferation, inhibits senescence, and facilitates transformation." (PMID 29237490, 2017). "The pooled hazard ratio (HR) revealed that over-expressed SOX9 was significantly associated with poor overall survival (OS) for cancer victims in multivariate analysis (HR: 1.66, 95% CI: 1.36–2.02)." (PMID 29348895, 2017). "CTGF and SOX9, both of which were found to be downregulated in this study, have also been implicated in cancer invasion." (PMID 27600078, 2016). "SOX9 is an important transcription factor required for development and has been implicated in several types of cancer." (PMID 26578390, 2015). "SOX9 is overexpressed in a variety of malignancies and is associated with cancer development or progression." (PMID 26384302, 2015). "Specifically expressed in myoepithelial cells and breast basal-like carcinomas, SOX9 and SOX10 have proven to be negatively associated with FOXA1, which encodes FoxA1 transcription factor, an essential regulator of mammary ductal morphogenesis." (PMID 25962646, 2015). "Gene expression profiling in NF1-associated benign and malignant tumours identified relatively widespread deregulation of genes in developing schawnn cells and in particular, the SOX9 gene seems to be essential for MPNST cell survival." (PMID 20687928, 2010). "Recently, increasing evidence has implicated SOX9 in cancer pathogenesis." (PMID 41031891, 2025). "These CSCs interact with immunosuppressive immune cells thereby constructing immune‐suppressive niche, and inflammatory cancer‐associated fibroblast (iCAFs) to enhance stemness through upregulation of SOX9 and OLFM4, promoting drug resistance and proliferation via the AREG‐ERBB2 signaling pathway." (PMID 39950944, 2025). "Furthermore, SOX9 is upregulated across various cancer types and is strongly linked to poorer overall survival in GBM." (PMID 40692865, 2025). "In breast cancer, Sox2, Sox4, Sox9, and Sox10 may be associated with cancer stem cell properties and resistance to therapy." (PMID 40980324, 2025). "However, with sustained SOX9 expression, the transcriptional changes continued, and by W6–12, cancer-associated features appeared." (PMID 37488435, 2023).
cancer (continued). "A third possibility is that heterozygous SOX9 mutations confer phenotypic plasticity, defined as the ability to change cell states, which is increasingly being recognized for its contributions to cancer initiation, progression, metastasis, and drug resistance." (PMID 37621863, 2022). "Even with the pieces of evidence presented in this study, which was limited by reliance on cancer cell lines, better model systems and more systematic evaluation are required to rigorously examine whether heterozygous SOX9 mutations confer plasticity." (PMID 37621863, 2022). "Given that a subset of KEAP1 mutations lead to elevated SOX9 protein levels and tumorigenesis, our findings suggest that targeting SOX9 in cancer patients bearing such mutations could be a viable stratified approach for their treatment." (PMID 33173725, 2020). "Moreover, several studies have linked SOX9 to cancer initiation and the regulation of the population of cancer stem cells (CSCs) in multiples tissues, promoting processes associated to this specific population such as metastasis or chemoresistance." (PMID 31941916, 2020). "Recent findings have shown that ectoderm- and endoderm-derived tissues continue expressing stem-cells related transcription factors of the SOX-family of proteins such as SOX2 and SOX9 which have been implicated in the presence of cancer stem-like cells (CSCs) in tumors." (PMID 31057614, 2019). "Interestingly, the only characterized gene in the locus tagged by rs2241173 was SOX9 –the gene encoding transcription factor required for male sexual development, chondrogenesis/skeletal development and implicated in fibrosis and cancer." (PMID 30998689, 2019). "In addition, high level of SOX9 expression was reported to confer the properties associated with cancer stem cell (CSC) and correlate with epithelial–mesenchymal transition (EMT) through triggering signaling cascades including the WNT/β-catenin pathway." (PMID 29237490, 2017). "Clinico-pathological association of SOX9 immunostaining in all cancers." (PMID 26030748, 2015). "In addition, SOX9 has previously been implicated in invasive growth in other cancer types such as prostate cancer." (PMID 25865119, 2015). "The cause of SOX9 deregulation in cancer is another issue of interest." (PMID 26384302, 2015). "Sox9 has been established as a key regulator of tissue stem and progenitor cells during development in several organ systems, more recently has been linked to cancer stem cell function." (PMID 25527186, 2014). "In order to determine transcription factors in cancer-associated fibroblast activation, which play a role in cell proliferation and cancer progression, we evaluated the expression of several transcription factors, including SOX9, POU5F1, ZEB1, JUN, and FOS in the HRTPT cell line exposed to arsenite." (PMID 40699854, 2025). "In addition, loss of APC and APC2 results in increased expression of the Wnt signaling target genes cMYC and Sox9, lending further weight to the clinical relevance of the loss of both genes, especially for a difficult to treat sub-population of human cancer patients." (PMID 27694902, 2017). "Here we show that NKG2D promotes cancer cell plasticity by induction of phenotypic, molecular, and functional signatures diagnostic of the epithelial–mesenchymal transition, and of stem-like traits via induction of Sox9, a key transcriptional regulator of breast stem cell maintenance." (PMID 25291178, 2014). "SOX2/SOX9 enable natural killer cell evasion by downregulating major histocompatibility complex class I markers in cancer cells." (PMID 41268614, 2026).
cancer (continued). "This complex enhances the nuclear retention and transcriptional output of YAP/TAZ, directly activating genes essential for cancer stem cell maintenance (e.g., SOX9, OCT4) and EMT progression." (PMID 40746536, 2025). "We found evidence that, upon acute exposure to platinum, nearly all cancer cells upregulate SOX9, thereby inducing overall stem state–relevant genes." (PMID 41031891, 2025). "Jade family PHD finger 3 (JADE3) is related to cell proliferation and apoptosis and increases cancer stem cell-like properties along with SOX9." (PMID 41440381, 2025). "We showed that CD44v6 expression correlated with the expression of sex-determining region Y-box 9 (SOX9), a cancer stem cell marker in murine liver tumours." (PMID 41168417, 2025). "The transcription factor SRY box 9 (SOX9) is a key regulator involved in various diseases, including cancers." (PMID 40428248, 2025). "Findings revealed that SOX9 is significantly upregulated in GBM and other cancer types, and its high expression is strongly associated with worse overall survival in GBM." (PMID 40692865, 2025). "These include Sox9 and several other transcription factors being involved in EMT and regulated by Sox9 upon development and cancer formation." (PMID 41223283, 2025). "SOX9 is a central transcriptional regulator with dualistic roles in disease, functioning as an oncogene in numerous cancers and a pro-regenerative factor in inflammatory and degenerative conditions, making it a compelling yet complex therapeutic target." (PMID 41293317, 2025). "Given its significant role in immunobiology, SOX9 represents a promising therapeutic candidate for cancer and immune-related diseases." (PMID 41293317, 2025). "In recent years, SOX9 has been reported to play an important role in many diseases and cancers, and is a promising target, but it has been rarely reported in GBM." (PMID 40692865, 2025). "Treatment with the NTN1 antibody decreased FAK phosphorylation, downregulated ZEB1 and SOX9, reduced Ki-67+ proliferating cancer cells, and also decreased PGP9.5+ and TH+ nerves." (PMID 40777309, 2025). "Future work will be required to unveil the relevance of the HIF1a-SOX9 blockage, shown to limit cell fate re-specification during regeneration, for clinically relevant models such as wound healing and cancer, where plasticity is known to operate." (PMID 41309646, 2025). "Recently, as an important transcription protein, SOX9 has attract a lot of attention due to the relationships between SOX9 and cancer progression and drug resistance." (PMID 40428248, 2025). "Accumulating studies reveal that SOX9 is highly expressed in various cancers, and its upregulation correlates with enhanced cancer cell proliferation, invasion, and metastasis." (PMID 40240356, 2025). "SOX9 is a transcription factor involved in regulating cancer stem cells (CSCs) across various cancers and functions as an oncogene." (PMID 40374599, 2025). "Mutations in KEAP1 impede its ubiquitin ligase activity toward SOX9, promoting cancer cell growth and tumorigenesis by stabilizing SOX9." (PMID 40240356, 2025). "The SRY-box transcription factor 9 (SOX9) is a well-characterized oncoprotein critical for the pathogenesis and progression of multiple cancers, including NSCLC." (PMID 41428171, 2025). "Some of them, including Sox9, are known to be involved in the development of MPNSTs and other cancers." (PMID 41223283, 2025). "The result indicated that the expression levels of SOX9 were positively correlated with sensitivity to the most current cancer-targeted drugs or chemotherapy drugs." (PMID 40692865, 2025). "RT recruits activated neutrophils to irradiated lung tissue, which promotes Notch–Sox9 signaling in infiltrating cancer cells, inducing stem-like, pro-metastatic traits." (PMID 40805288, 2025). "EMT pathway gene expression changes were prominent in human CRCs with low SOX9 expression and in a mouse cancer model with high SOX2 expression." (PMID 40179020, 2025).
cancer (continued). "SOX9 serves as a pivotal transcription factor, exerting a multifaceted influence by governing cancer stem cells (CSCs) and epithelial-mesenchymal transition (EMT) in various cancer types." (PMID 40240356, 2025). "Glycolysis-regulating genes such as SOX9, ABCB6 and ENO1, were associated with metabolic reprogramming essential for cancer progression." (PMID 39920655, 2025). "SOX2 and SOX9 are frequently overexpressed in multiple cancer entities, suggesting a link between malignancy and stemness." (PMID 39180200, 2025). "Combined Sox9 and Apc biallelic inactivation led to lesions with high-grade dysplasia and invasion typical of carcinoma." (PMID 40179020, 2025). "HNF4A binding on the Sox9 promoter inhibited the formation of LYZ+ cancer cells exhibiting Paneth cell characteristics." (PMID 38659853, 2024). "The Yap/SOX9 axis is known to activate cancer stem cell features and has demonstrated involvement in promoting the proliferation and metastasis of various cancer types, including gastrointestinal carcinoma." (PMID 38721276, 2024). "In advanced prostate cancer, the genetic loss of Zbtb7a activates SOX9-targeted genes such as H19 and MIA, ultimately reducing the expression of integrin to promote cancer metastasis." (PMID 38331879, 2024). "Of note, MD tumoroids were characterized by an increased, yet heterogeneous expression of SOX9, a pro-metastatic TF involved in cancer cell dormancy 11,22." (PMID 38503727, 2024). "The ongoing study of Sox9 and its role in cancer holds great promise for the future of cancer research and treatment." (PMID 38978960, 2024). "Among the SOX genes, the transcription factors (TFs) SOX2 and SOX9 have been pointed as important players in different types of cancer." (PMID 38275880, 2024). "SOX9 is also recognized as a marker of PDAC cancer stem cells (CSCs), contributing to their stemness properties." (PMID 38811540, 2024). "It is likely that the impact of SOX2 and SOX9 on the response of cancer cells to irradiation is highly context dependent and critically depends on other epigenetic and genetic alterations." (PMID 38275880, 2024). "A portion of chromosome 17, including the pan-cancer gene SOX9, was deleted at q24.3 and q25.1 due to the translocation." (PMID 39200124, 2024). "The heightened expression of SOX9 in clinical cancer tissues promotes neoplastic growth of cancer cells." (PMID 38570607, 2024). "Droplet RNAseq analysis demonstrates that these ductal clusters express embryonic multipotent progenitor cell markers Sox9, Pdx1, and Nkx6-1, and genes involved in actin cytoskeleton regulation, inflammation responses, organ development, and cancer." (PMID 38206366, 2024). "Altogether, the results presented here demonstrate that a prominent SOX2 expression was only detected in cancer cells, while SOX9 expression was also detected in stromal cells of the TME." (PMID 38275880, 2024). "They further annotated that the knockout of SNHG14 and SOX9 suppressed tumour migration and invasion by upregulation of miR-206 and increased apoptosis in cancer cells, all of which was reversed by the repression of miR-206." (PMID 40176927, 2024). "The role of SOX9 expression in diverse stromal cells of the TME is not explored yet and these findings provide new insights into the potential role of SOX9 in the mutual crosstalk of cancer cells with the microenvironment." (PMID 38275880, 2024). "Through modulation of the gut microbiota SOX9 or mmu circ 0000730 dramatically downregulated and decreased cancer cell invasion." (PMID 38192436, 2024). "YAP can regulate the transcription of SOX9, and YAP-driven SOX9 expression is involved in cancer development." (PMID 38255951, 2024).